TRIM72 (tripartite motif containing 72)
Diseases named in the same sentence as TRIM72 in open-access papers (continued):
Sharing a sentence is not in itself a finding about the gene and the disease.
infection (4 papers, 2020 to 2024). The state of being infected such as from the introduction of a foreign agent such as serum, vaccine, antigenic substance or organism. "From the results, we can see that RABV titer dramatically increased in the Trim72-/- group compared with the WT group both at 24 h and 48 h post-infection." (PMID 38408103, 2024). "Unlike the kidneys from vehicle-treated controls, kidneys from the Trim72-treated mice were smaller, less grossly pathologically swollen and pale, and had less prominent nodules at 7 days after infection." (PMID 39585917, 2024). "Histopathologic analysis also demonstrated that the kidneys of Trim72-/- mice exhibited increased renal inflammation and more C. albicans burden at 2 days after infection." (PMID 39585917, 2024). "The fungal load in other organs such as liver, lung and spleen in Trim72-treated mice also showed a decreasing tendency at 2 days, declined significantly at 4 days, and was basically cleared at 7 days post-infection." (PMID 39585917, 2024). "It was found that the TRIM72 expression level in N2a cells transfected with 0.5 μg of TRIM72 expressing vector presents a comparable level of TRIM72 in RABV infected N2a cells at 48 h post-infection." (PMID 38408103, 2024). "TRIM72 over-expression reduced the viral titer of rRABV, while there were almost no obvious changes in viral titers between the vector group and the TRIM72 over-expression group during rRABV-M-K195A infection." (PMID 38408103, 2024). "In addition, serum concentrations of blood urea nitrogen and serum creatinine, as well as NGAL expression levels in renal tissue, were significantly lower in Trim72-treated mice than in vehicle-treated mice at 7 days after infection." (PMID 39585917, 2024). "In this study, we found that TRIM72, a member of the TRIM protein family, was increased in neuronal cells and mouse brains following rabies lyssavirus (RABV) infection." (PMID 38408103, 2024). "From the results we can see RABV titer was dramatically decreased post TRIM72 over-expression no matter at 24 h or 48 h post-infection." (PMID 38408103, 2024). "For the in vitro experiments, primary neuron cells were isolated and cultured, and then the neuron cells were infected with RABV at varying multiplicities of infection (MOI) for 36 hours (h) and the mRNA level and protein level of TRIM72 were analyzed by qPCR and western blotting." (PMID 38408103, 2024). "Then TRIM72-flag over-expression vector or empty vector was individually transfected into N2a cells for 12 h and then RABV was infected (MOI = 0.01), the cells were collected at 24 h and 48 h post-infection, and the RABV N mRNA level and vRNA level were analyzed by qPCR." (PMID 38408103, 2024).
myopathy (3 papers, 2021 to 2022). A disease of the muscle in which the muscle fibers do not function properly. "Multiple lines of evidence support that TRIM72/MG53 is an important component of the membrane repair process, including studies showing increased membrane repair when TRIM72/MG53 is overexpressed and that a TRIM72/MG53 knockout mouse displays defective membrane repair and a progressive myopathy." (PMID 35563723, 2022).
infectious disease (2 papers, 2022 to 2024). A disorder directly resulting from the presence and activity of a microbial, viral, or parasitic agent in humans. "Previous studies have also pointed the important role of Trim72 in some infectious diseases." (PMID 39585917, 2024).
TRIM72 also shares sentences with these, for which no sentence is quoted: metabolic disorders (14 papers); metabolic syndrome (13); type 2 diabetes (7); cardiomyopathy (4); Hyperglycemia (4); ischemic heart disease (4); non-small cell lung carcinoma (4); viral infection (4); acute myocardial infarction (3); atherosclerosis (3); cardiac hypertrophy (3); colorectal carcinoma (3); heart failure (3); acute lung injury (2); aortic valve disease (2); atrial fibrillation (2); colorectal tumors (2); dysferlinopathy (2); Glucose intolerance (2); heart disease (2); hepatocellular carcinoma (2); Hypercholesterolaemia (2); Hyperinsulinemia (2); hyperlipidemia (2); Hypertension (2); metastatic tumors (2); abscess (1); acute coronary syndrome (1); Alzheimer disease (1); androgen excess (1).
A further 27 diseases each share a sentence with TRIM72 in 1 paper.